ATRX (ATRX chromatin remodeler)
Diseases named in the same sentence as ATRX in open-access papers (continued):
Sharing a sentence is not in itself a finding about the gene and the disease.
astrocytomas (continued). "In this context, it has been reported that the majority of IDH-mutant astrocytomas of all grades harbour truncating mutations in ATRX, which are mutually exclusive to 1p/19q codeletion and can be detected by the immunohistochemical loss of ATRX protein." (PMID 34165590, 2021). "However, loss of ATRX appears to be less sensitive in PMMRDIA than for conventional supratentorial IDH-mutant astrocytoma to identify cases with a rare IDH-mutation." (PMID 33216206, 2021). "The IDH1 and ATRX molecular group was associated with tumor growth in univariable analysis but not in multivariable analysis, which only demonstrated a marked separation in survival in the astrocytoma with 1p/19q LOH and IDH mutation." (PMID 32388499, 2020). "The astrocytoma tumor tissue samples and PDCs all shared the missense ATRX mutation G1567D." (PMID 32904945, 2020). "It should be noted that thismutation is more typical of young patients and can serve as a diagnostic and aprognostic factor, since it allows differentiation of astrocytomas andoligodendrogliomas and also because it is associated with a more benignprognosis (in case of lost ATRX activity)." (PMID 31413876, 2019). "Thus, tumors carrying mutations in the IDH gene concurrently with 1p/19q codeletion are classified as oligodendrogliomas, while those bearing mutations in IDH and ATRX are referred to as astrocytomas, and IDHwt tumors are identified as primary glioblastomas." (PMID 31435515, 2018). "ATRX loss is characteristic in the refinement of the diagnosis of IDH mutant astrocytomas." (PMID 27713914, 2016). "In addition, ATRX alterations were found to be frequently present in neurofibromatosis (type 1)-associated high-grade astrocytoma and were associated with in a variety of functional (impaired cognition, attention deficits and autism spectrum disorder) abnormalities." (PMID 38315329, 2024). "We found an association between mutations in glutamate receptor genes, the glutamate-S-transferase gene, and ATRX with DRE in patients with low-grade astrocytoma who presented with preoperative seizures." (PMID 40103938, 2025).
astrocytomas (continued). "Mutually exclusive with 1p/19q codeletion; used diagnostically (ATRX IHC) to confirm astrocytoma subtype." (PMID 41346390, 2025). "Loss of ATRX function, a diagnostic criterion of IDH-mutant astrocytoma, is closely associated with alternative lengthening of telomeres (ALT), a telomere maintenance mechanism (TMM)." (PMID 41422096, 2025). "ATRX protein expression is retained, distinguishing oligodendrogliomas from astrocytomas, which frequently lose ATRX expression." (PMID 40937216, 2025). "DRG2 was reported to be significantly under expressed in IDH1-mutant astrocytoma, which are frequently ATRX-mutant/ALT-positive." (PMID 39921567, 2025). "Histopathological analysis confirmed the diagnosis of astrocytoma IDH-mutant CNS WHO grade 4 with ATRX negativity." (PMID 40282523, 2025). "Inactivating mutations in ATRX, defining molecular alterations in IDH-mutant astrocytomas, have been implicated in dysfunctional immune signaling." (PMID 38272925, 2024). "The diagnosis was in favor of astrocytoma IDH mutant (IDH1 R132H positive, ATRX mutation, KI67-MIB1 70%, MGMT promoter methylation 55.55%), WHO grade 4." (PMID 39335096, 2024). "In tumors that are IDH mutant and ATRX wild type (WT), 1p-19q co-deletion is necessary to establish a diagnosis of oligodendroglioma, while IDH mutant –ATRX mutant patients can be diagnosed with IDH mutant astrocytoma." (PMID 38662171, 2024). "We demonstrated that ATRX- mutant astrocytomas display a more pro-inflammatory gene expression profile compared to oligodendroglioma counterparts." (PMID 38272925, 2024). "The next marker to be applied is ATRX, which helps distinguish astrocytomas from oligodendrogliomas." (PMID 39165459, 2024). "TERT mutations are found in many glioblastomas, whereas mutations of the X-linked gene of α-thalassemia (ATRX), leading to inactivation of the ATRX protein and induction of ALT, are found in many IDH-mutated astrocytomas." (PMID 37626776, 2023).
astrocytomas (continued). "We knock out the chromatin remodeler ATRX, which suffers loss-of-function alterations in most IDH-mutant astrocytomas, in an IDH-mutant immunocompetent intracranial murine model." (PMID 34763709, 2021). "H3K27me3 was retained in 2/60 oligodendrogliomas with retained ATRX, and in 3/6 IDH-mutant astrocytomas, two of which had lost and one retained ATRX." (PMID 34165590, 2021). "This was addressed by performing double IF for ETNPPL and IDH1 R132H (1 oligodendroglioma) and ATRX (2 astrocytomas)." (PMID 32218467, 2020). "ATRX loss-of-function mutations occur in about 75% of World Health Organization grade II and III astrocytoma and IDH-mutated secondary GBM cases." (PMID 33194637, 2020). "ATRX was frequently affected by small somatic frameshift deletions or stop gain insertions in 28% of the sequenced astrocytomas." (PMID 32604718, 2020). "It should be noted that the molecular profiles of astrocytomas in childrendiffer significantly from the adult variants and mainly contain mutations insuch genes as BRAF, H3F3A, and ATRX." (PMID 31413876, 2019).
astrocytomas (continued). "Regarding ATRX status, high-grade astrocytomas have been reported with concomitant ALT phenotype and ATRX loss, in both adult and paediatric tumours." (PMID 29751586, 2018). "Consistent with our previous report, ATRX mRNA expression was significantly different in grade II-IV astrocytic tumors (p < 0.0001) and reduced in grade II astrocytomas compared with in pGBMs and AAs (p < 0.0001, p < 0.05, respectively)." (PMID 25971279, 2015). "TERT mutations are mutually exclusive with ATRX (alpha thalassemia mental retardation syndrome X linked) mutations, which are instead seen in the majority of WHO grade II-III astrocytomas and secondary glioblastomas." (PMID 25943885, 2015). "Consistent with our report, ATRX expression characteristically decreased in grade II astrocytomas and secondary glioblastoma and low ATRX expression was correlated with favorable survival of patients in astrocytic tumors." (PMID 25971279, 2015). "In our cohort, low ATRX mRNA expression was detected in 68% of astrocytomas, 50% of anaplastic astrocytomas and 41.6% of glioblastomas." (PMID 24810474, 2014). "We and others showed ATRX to be mutated in pediatric HGA and adult IDH-mutant astrocytomas and showed alternative lengthening of telomeres (ALT) to be associated with ATRX mutations." (PMID 25077668, 2014). "Loss of nuclear ATRX is enough to establish the diagnosis of astrocytoma without additional testing for 1p/19q codeletion." (PMID 40949165, 2025). "ATRX was mutated in only one case (IDH-mutant astrocytoma), while no mutation of the TERT promoter was found." (PMID 41517303, 2025). "Notably, cases harboring canonical alterations such as IDH1 and ATRX tended to segregate together, suggesting a transcriptional signature associated with the IDH-mutant astrocytoma subgroup." (PMID 41517303, 2025). "While the association between mutations in ATRX and IDH1 has been known for over a decade, the details of their interaction and basis for recurrent co-occurrence in astrocytoma remains unclear." (PMID 38272925, 2024).
astrocytomas (continued). "While the association between mutations in ATRX and IDH1 has been known for over a decade, the details of their interaction and basis for frequent co-occurrence in astrocytomas remains unclear." (PMID 38272925, 2024). "Out of 11 cases of astrocytoma, all exhibited IDH mutation and ATRX loss." (PMID 39165459, 2024). "Oligodendrogliomas are defined by 1p/19q codeletion, while astrocytomas are 1p/19q non-codeleted tumors with ATRX loss." (PMID 36566461, 2023). "ATRX is recurrently mutated in IDH-mutant astrocytoma, H3 K27-altered diffuse midline glioma, H3 G34-mutant diffuse hemispheric glioma and high-grade astrocytoma with piloid features (HGAP)." (PMID 36933012, 2023). "Immunohistochemical loss of ATRX expression (69.2%, 9/13) did not appear as frequent as in astrocytoma supratentorial (92%, 46/50, p = 0.05, Fisher’s exact test) and high-grade astrocytoma supratentorial (86.8%, 33/38, p = 0.154, Fisher’s exact test)." (PMID 33216206, 2021). "Thus, ATRX immunostaining has been suggested as an alternative low-cost marker to differentiate IDH-mutant astrocytomas from oligodendrogliomas." (PMID 34165590, 2021). "H3K27me3 was lost in 58/60 oligodendrogliomas with retained (n = 47) or non-conclusive (n = 11) ATRX staining, 3/6 IDH-mutant astrocytomas with ATRX loss, and 3/3 IDH-wt astrocytomas." (PMID 34165590, 2021). "In order to distinguish several cell populations in IDH-DGIIG tumors, we examined three diffuse grade II astrocytoma tumors with IDH1 R132H and ATRX mutations and three diffuse grade II oligodendroglioma tumors with an IDH1 R132H mutation and a 1p19q codeletion." (PMID 33925547, 2021). "However, we observed a loss of ATRX staining in 4% (2/45) of oligodendrogliomas and retained ATRX staining in 37% (11/30) of IDH Mut astrocytomas." (PMID 34020723, 2021). "Interestingly, large deletions of almost the whole ATRX gene have only rarely been reported in other tumor types, such as astrocytomas, pancreatic NETs, and pheochromocytomas and paragangliomas." (PMID 33106857, 2021). "Interestingly, we also confirmed that TGF-β signaling was up-regulated in ATRX-mut DIGs or astrocytomas in the independent public dataset, highlighting the tumor-promoting role of TGF-β in DIGs with ATRX mutations." (PMID 32120790, 2020). "The authors classified 133 patients from two tumor databases in three groups, according to the molecular characteristics of the tumors: Group O (IDH mutant, 1p/19q codeleted oligodendrogliomas), Group A (IDH mutant, ATRX inactivated astrocytomas), and Group G (IDH wild-type, GBM-like)." (PMID 33228171, 2020).